PLK1 (polo like kinase 1)
Diseases named in the same sentence as PLK1 in open-access papers (continued):
Sharing a sentence is not in itself a finding about the gene and the disease.
cancer (continued). "Furthermore, miR-486-5p showed a positive effect on the expression of PLK1, involved with a proper cell division process and with controversial behavior in cancer, in which it is described both as an oncogene and an oncosuppressor." (PMID 33227890, 2020). "Indeed, research has shown that KRAS mutant cancer cells are highly sensitive to PLK1 inhibition, wherein cancer cells carrying the oncogenic mutation KRAS were sensitive to PLK1 depletion by shRNA or to treatment with PLK1 inhibitors." (PMID 32486290, 2020). "Hence, further elucidating the detailed regulatory mechanism(s) of PLK1 is required to pave a way for PLK1-targeted cancer treatment." (PMID 33106477, 2020). "Either way, as a consequence of CCNA2 upregulation, cancer cells mayface an unavoidable dependence on PLK1 to prevent mitotic catastrophe by disrupted spindle assembly." (PMID 32486290, 2020). "Importantly, cell cycle genes play an essential role in cancer development and certain gene products, such as polo-like kinas 1(PLK1) and Aurora Kinases, are over-expressed in human cancers and are therefore attractive drug targets for cancer therapy." (PMID 32424219, 2020). "Because of the differential effects of phosphorylation residues in PLK1, the overexpression of PLK1 in cancer could promote migration, invasion, and colonization, through the differential phosphorylation status." (PMID 31548612, 2020). "Thus, the active version of PLK1 promotes the invasiveness of cancer cells as well as cell motility." (PMID 31548612, 2020). "A previous study has demonstrated that CIP2A could regulate the cell cycle by targeting the polo-like kinase (Plk1) and protect cancer cells from apoptosis and senescence." (PMID 32321509, 2020). "Plk1 inhibitors including THAP may have targeted therapeutic activity to treat Plk1-overexpressed cancer." (PMID 32977631, 2020). "High expression of PLK1, a proto-oncogene and critical regulator of several cellular events, including cell division, DNA replication, and DNA damage recovery, has been found in several cancers." (PMID 31548612, 2020). "Thus, the increasing activity of PLK1 seems to be a mechanism by which cancer cells can continue cell division despite DNA damage, resulting in increased levels of CIN." (PMID 33066048, 2020). "Thus, the presence of the functional domain of PLK1 is important in inducing cancer metastasis and tumorigenicity, which are accelerated by active PLK1 in NSCLC." (PMID 31548612, 2020). "Notably, the transcription factor MYBL2 is a central regulator of cell survival, proliferation and differentiation in cancer, and PLK1 and TOP2A are druggable by clinically advanced inhibitors." (PMID 32824422, 2020). "Expression of PLK1 is frequently elevated in various human cancers, including advanced PCa39." (PMID 32704044, 2020). "Therefore, PLK1 inhibition has been considered as a potential strategy to develop novel drugs for the treatment of various types of cancer." (PMID 33106477, 2020). "Several studies have shown that PLK1 is involved in the invasion and metastasis of cancer." (PMID 32463161, 2020). "In this regard, understanding the role of BORA in cancer cells will add valuable insights into BORA/PLK1-related mechanisms and might offer novel opportunities for therapeutic intervention in OC." (PMID 32268485, 2020). "However, clinical trials with PLK1 inhibitors as cancer drugs have generally displayed poor responses or adverse side-effects." (PMID 33066048, 2020). "The processing and timing of key cell cycle events can become dysregulated, leading to CIN through abnormal PLK1 activities, and in this review, we discuss therapeutic avenues that may arise from near-ubiquitous PLK1 deregulation in cancer cells." (PMID 33066048, 2020). "Many mitotic kinases in addition to PLK1 are elevated across different cancer types." (PMID 33066048, 2020). "Can we get a wider picture of this Plk1 dichotomy in a pan-cancer analysis?" (PMID 30862113, 2019).
cancer (continued). "Shortly after Plk1 was described in mammals, growing shreds of evidence showed that Plk1 is commonly upregulated in a wide variety of tumors, and its overexpression has been validated as a prognostic marker in a subset of these cancers." (PMID 30862113, 2019). "Based on these results together with their known inhibitory effects on cancer cell proliferation and metastasis, combined treatment with both PLK1 and PTP4A1 inhibitors could be an effective therapy for metastatic breast cancer." (PMID 31097707, 2019). "In addition, we also illustrated that CHK1, CDK1, and PLK1 were associated with SLC16A7 in MDA-MB-231 and A549 cancer cells, providing a 75% validation ratio among four selected candidates." (PMID 31311925, 2019). "PLK1 inhibitors have been developed to experimentally treat different cancer types." (PMID 31730000, 2019). "Furthermore, PLK1 hyper-activation contributes to cancer therapeutic resistance to chemotherapy and radiotherapy." (PMID 31730000, 2019). "However, BI2526 treatment profoundly inhibits MuSCs function during muscle regeneration, cautioning the potential side effect of PLK1 inhibition in skeletal muscle homeostasis and cancer cachexia." (PMID 31393265, 2019). "Polo-like kinase 1 (Plk1) has been shown to be involved in chemoresistance, so Plk1-targeted therapies could possibly reduce or eliminate the chemoresistance of cancer cells against anticancer drugs." (PMID 31866857, 2019). "Polo-like kinase 1 (PLK1) has been recognized as a valuable target in cancer treatment due to the prognostic implication of PLK1 in cancer patients and its clinical relevance between the overexpression of PLK1 and the reduced survival rates of several carcinoma patients." (PMID 31100782, 2019). "Significantly, many types of cancer, including pediatric tumors, also express high PLK1 levels." (PMID 31824851, 2019). "Finally, there are also data available on the involvement of Plk1 in cancer cell migration and invasion." (PMID 30859681, 2019). "Inversely, PLK1 depletion re-sensitizes cancer cells to therapy, overcoming therapeutic resistance." (PMID 31730000, 2019). "Already having evidence on how Plk1 can collaborate with the tumor process, and that it can also function as a tumor suppressor; it is of interest to test if this paradigm can be reflected in cancer patients, in terms of clinical outcome." (PMID 30862113, 2019). "Moreover, Chorn LNP delivered siRNA against polo-like kinase 1 (Plk1), a disease related gene in cancer cells and efficiently suppressed the expression of the gene, resulting in significant morphological changes in the cell nuclei." (PMID 31546908, 2019). "Further work to understand PLK1 also has potential implications for cancer treatment." (PMID 31393265, 2019). "Moreover, the expression patterns of the thermogenes HSPA4 and HSP90AA1 and the oncogene PLK1 were found to be positively correlated in diverse types of cancers." (PMID 31814876, 2019). "Therapy-induced cellular senescence in cancer cells, or at least a senescence-like phenotype, has already been shown to be a crucial phenotype after chemotherapy, radiotherapy, and more recently also after Plk1 inhibition." (PMID 31795121, 2019). "It is reported that miR-100 targets Plk1 in certain cancer cells." (PMID 30135525, 2018). "Relevant studies have revealed the PLK1 was involved in the mechanism of cancer growth." (PMID 30133120, 2018). "Although Plk1 mutations are not frequent in human cancer cells, the only mutations found in a few cancer cell lines generate Plk1 isoforms with decreased protein stability and reduced protein levels." (PMID 30069007, 2018).
cancer (continued). "The overexpression of Polo-like kinase 1 (Plk1) promotes various cancers in humans; sporadic evidence suggests Plk1 could act as a tumor suppressor but the molecular basis for this effect are unclear." (PMID 29549256, 2018). "PLK1 is overexpressed in many types of cancer, which correlates with poor prognosis." (PMID 29899826, 2018). "Indeed, many researchers have reported the abnormal expression of Plk1 and Cdc25C in several cancer cells." (PMID 29531821, 2018). "Moreover, the in vitro experiment verified that the PLK1 inhibition significantly increased the expression of HLA molecules in various cancers." (PMID 30631355, 2018). "Furthermore, we found that a majority of the 24 HLA genes analyzed showed significantly negative expression correlations with the PLK1 expression in the 12 cancer types in which the PLK1 expression negatively correlated with the HLA activity." (PMID 30631355, 2018). "PLK1 plays a pivotal role during the M phase and cytokinesis in cancer cells." (PMID 29765534, 2018). "PLK1 likely inhibits antitumor immunity, and the elevated tumor immunity may enhance the sensitivity of cancer cells to PLK1 inhibitors." (PMID 30631355, 2018). "Volasertib, also known as BI 6727, is a small molecule inhibitor of the polo-like kinase 1 (PLK1) protein, and being developed as an anti-cancer agent with the potential combination therapy for those untreated patients who are ineligible for intensive induction therapy." (PMID 29456860, 2018). "Second, cancer immunotherapy may enhance tumor immunogenicity, which in turn increases the sensitivity of cancer cells to PLK1 inhibitors." (PMID 30631355, 2018). "In most cancer cells, mitotic arrest induced by PLK1 inhibition triggers apoptosis." (PMID 29339720, 2018). "Based on the essential role of PLK1 during mitosis of all proliferating cells and its enriched expression in human cancer tissues, we set out for the investigation of the role of PLK1 in genetically unstable cancer." (PMID 29549256, 2018). "Strong positive correlations between human cancer metastasis and the up-regulation of Plk1 have been reported (12, –, 14); however, the mechanism by which Plk1 deregulation promotes metastasis and tumorigenesis remains largely unknown." (PMID 29191835, 2018). "In addition, in 6 cancer types (TGCT, PRAD, CESC, LIHC, KICH, and STAD), the upregulation of PLK1 was associated with higher levels of NK cell infiltration, and in 1 cancer type (LUAD), we observed an opposite trend (Spearman correlation, FDR<0.1)." (PMID 30631355, 2018). "These key roles of Plk1 mean that Plk1 inhibitors are promising cancer therapeutics." (PMID 29757235, 2018). "The validation of PLK1 in multiple animal models revealed PLK1 as an important cancer target." (PMID 29899826, 2018). "However, Plk1 inhibition has been shown to sensitize cancer cells to gemcitabine and vincristine in vitro." (PMID 29402316, 2018). "Notably, HLA-A, HLA-DPA1, HLA-DQB1, HLA-DRA, HLA-DRB1, HLA-DRB5, and HLA-J consistently negatively correlated with the PLK1 expression in the 12 cancer types." (PMID 30631355, 2018). "Moreover, up-regulation of Polo-like kinase 1 (Plk1) positively correlates with human cancer metastasis, yet how Plk1 deregulation promotes metastasis remains elusive." (PMID 29191835, 2018). "It indicated that higher levels of B cells, NK cells, or TILs could promote the sensitivity of cancer cells to PLK1 inhibitors." (PMID 30631355, 2018). "Polo like kinase-1 (PLK1) has received attention as a candidate anti-cancer target as it plays a critical role in different stages of cell cycle progression and mitosis including mitotic entry, G2/M checkpoint, spindle assembly maturation, chromosome segregation, and mitotic exit." (PMID 29983892, 2018).
cancer (continued). "Thus, our findings suggest that PLK1 and PLK4 inhibition underlies the activity of Poloppin in triggering mitotic arrest, and in preferentially killing cancer cells that express mutant oncogenic KRAS." (PMID 28807782, 2017). "Plk1 is known to be overexpressed in many cancers and is now a target for cancer therapy." (PMID 28821799, 2017). "Here our novel results suggest that Plk1 inhibition could suppress cancer proliferation via both cell cycle progression and biosynthesis." (PMID 29138396, 2017). "Indeed, emerging evidence supports the notion that PLK1 is actively involved throughout the course of human cancer development." (PMID 28953239, 2017). "A wide variety of cancers including entities predominantly occurring in children overexpress PLK1." (PMID 28036269, 2017). "PLK1 overexpression is known to override the G2/M and spindle checkpoints induced by DNA damage, thereby promoting chromosome instability and aneuploidy and fostering cancer progression." (PMID 28036269, 2017). "Some genetic backgrounds have been proposed to sensitize cancer cells to PLK1 inhibition." (PMID 28036269, 2017). "Notably, Poloppin sensitivity persists in cancer cells resistant to an ATP-competitive PLK1 inhibitor, and Poloppin sensitizes mutant KRAS-expressing cells to clinically used inhibitors of the MET tyrosine kinase, opening opportunities for combination therapy." (PMID 28807782, 2017). "However, the molecular mechanisms underlying the differences in the regulation of the Plk1 and RSK1 signaling pathway between CSCs and cancer cells need to be elucidated." (PMID 28430578, 2017). "Up-regulation of PLK1 was found in tumorigenesis and tumor progression of diverse cancers." (PMID 28915707, 2017). "PLK1 expression is correlated to cancer aggressiveness, based on fast growth of cancer cells." (PMID 29383199, 2017). "Correlation of such data with clinical outcome may allow development of strategies for optimized (combinatorial) cancer therapies, to simultaneously target PLK1 and MTOR in tumors where MTORC1 is activated by PLK1 inhibition." (PMID 28102733, 2017). "Indeed, silencing of Plk1 levels by RNAi or inhibition of Plk1 activity by specific inhibitor is capable of decreasing the growth of most cancer cells, influencing mitotic spindle formation, and promoting apoptosis." (PMID 29138491, 2017). "High-level PLK1 expression has previously been reported in a variety of pediatric cancers." (PMID 28036269, 2017). "Therefore, Plk1 has drawn great attention and been regarded as a potential anti-cancer target in cancer therapeutic research." (PMID 28430578, 2017). "PLK1 has been reported as widely overexpressed in tumor samples from cancer patients, and its overexpression has been validated as a biomarker of poor prognosis in a variety of human cancers." (PMID 28953239, 2017). "Moreover, PLK1 has also been shown to play a critical role in the cell invasion and migration of many cancers." (PMID 29246203, 2017). "Because human cancers are frequently slow growing, inhibiting a cancer-addicted target, such as Plk1, could be particularly effective in achieving the full therapeutic potential of an anti-mitotic agent." (PMID 28721210, 2017). "Furthermore, PLK1 inhibition has been documented to enhance anti-cancer drug efficacy in a variety of types of human cancers." (PMID 28953239, 2017). "It is reasonable to speculate that targeting PLK1 has the potential for multi-dimensional actions against cancer, and ultimately paves the way for curative cancer treatments." (PMID 28953239, 2017).
cancer (continued). "Studies have demonstrated that PLK-1 is overexpressed in more than 50% type of cancers." (PMID 28415805, 2017). "Beyond this, our findings suggest that combinatorial targeting of MTORC1 and PLK1 may hold promise for cancer treatment." (PMID 28102733, 2017). "Since PLK1 plays a major role in regulating the cell cycle and maintaining genomic stability, it is believed that PLK1 controls cancer development through multiple mechanisms, including classic regulation of mitosis and cytokinesis, as well as response to cellular stress and cell survival." (PMID 28953239, 2017). "PLK1 overexpression has been found in many cancer cell lines and neoplastic tissues." (PMID 29246203, 2017). "Cancer cells depends on PLK1 for survival more than normal cells." (PMID 28008150, 2017). "Thus, Plk1 is an appealing therapeutic target for cancer treatment, and a number of Plk1 inhibitors are currently under preclinical or clinical trials." (PMID 27902479, 2017). "Notably, overexpression of PLK1 has been shown to stimulate cell proliferation and oncogenic transformation 21, while PLK1 depletion/inhibition triggers apoptosis in various cancer cell lines 22, 23, and impairs tumour growth in mice." (PMID 27862966, 2017). "Previous studies have shown that functional inhibition of Plk1 induces apoptosis in cancer cells." (PMID 27902479, 2017). "Our results show that the Plk1 phosphorylation sites in FoxM1b serve as a regulator for its repressor function, and they provide insights into how FoxM1b inhibits differentiation genes and activates proliferation genes during cancer progression." (PMID 28387346, 2017). "For example, in the seven cancer types (BLCA, ESCA, HNSC, KIRC, LIHC, STAD and UCEC) with both grade phenotype information and normal control samples, expression of AURKB, BUB1, FOXM1, HMMR, MYBL2, and PLK1 follows the pattern in five cancer types (BLCA, HNSC, KIRC, LIHC, and UCEC)." (PMID 28427185, 2017). "Another potential advantage of targeting the PBD is that while ATP-competitive inhibitors can abrogate all Plk1-dependent biochemical processes indiscriminately in both cancer and normal cells, PBD inhibitors interfere in only a subset of Plk1 functions that require a PBD-mediated biochemical step." (PMID 28721210, 2017). "The prognostic value of PLK1 in cancers is currently high profile." (PMID 29190933, 2017). "PLK1 is a fascinating multifaceted protein that targets many binding partners to ensure proper cell cycle progression and cell proliferation, and its deregulation contributes to the genesis of a broad range of human cancers." (PMID 28953239, 2017). "PLK-1 might provide a novel therapeutic target for resolving incurable diseases, such as Alzheimer’s, cancer." (PMID 28415805, 2017). "Here, we identify PLK1 as a physical MTORC1 interactor in human cancer cells." (PMID 28102733, 2017). "Polo-like kinase 1 (PLK1) is highly expressed in many cancers and essential for mitosis." (PMID 29228610, 2017). "Considering the success of anti-mitotic therapeutics and the remarkable advantages of targeting Plk1, there is ample reason to believe that further developing anti-Plk1 therapeutics may prove to be a worthwhile endeavor in the fight against cancer." (PMID 28721210, 2017). "Several PLK1 inhibitors are currently in clinical trials as cancer therapeutics." (PMID 28178660, 2017). "In addition to the superb binding specificity that PPI inhibitors can bring, Plk1 PBD inhibitors can provide an opportunity to selectively interfere with cancer-cell-enriched Plk1 PBD-binding targets." (PMID 28721210, 2017). "Cell cycle associated proteins are frequently aberrantly expressed in cancer and can be targeted using small molecular inhibitory compounds such as novel inhibitors of the BUB1-Polo-like-kinase 1 interaction and other cell cycle kinase inhibitors currently tested in preclinical studies." (PMID 29100315, 2017).